STAT3 (signal transducer and activator of transcription 3)
Diseases named in the same sentence as STAT3 in open-access papers (continued):
Sharing a sentence is not in itself a finding about the gene and the disease.
cancer (continued). "Moreover, drug-treated cancer cells exhibited increased production of STAT3 protein, overproduced superoxide and peroxides, and increased mitochondrial mass." (PMID 34674640, 2021). "For instance, mTOR/STAT3 is commonly dysregulated in various cancers." (PMID 33652661, 2021). "Consequently, activating the S100A7/RAGE pathway via STAT3 signaling sustains angiogenesis and thus stimulates cancer promotion in breast cells." (PMID 34950252, 2021). "STAT3 is a molecular in STAT family with crucial effects on cell proliferation, differentiation, migration, and angiogenesis in cancer progression; persistent STAT3 activation is found to promote chronic inflammation, which increases susceptibility of healthy cells to carcinogenesis." (PMID 34337082, 2021). "In addition, STAT3 is recognized as an oncogene, and its activity is increased by ~50% in various cancers, including OSCC." (PMID 34769467, 2021). "Crosstalk between NF-κB and STAT3 signaling exists in a variety of cancers." (PMID 33990540, 2021). "By secreting CCL5, M2-TAMs may activate signal STAT3 leading to enhanced cancer cell proliferation and invasion/metastasis formation." (PMID 34638423, 2021). "Duan found that the differential expression of STAT3 in GC was closely related to pathological features such as cancer tissue infiltration and lymph node metastasis, and some studies have suggested that this target was related to the treatment and prognosis of GC." (PMID 33953786, 2021). "Interestingly, NF-κB and STAT3 also physically interact and coregulate transcriptional pathways in cancer." (PMID 34178628, 2021). "By modulating both immunosuppressive cells and the immunosuppressive function of cancer cells, inhibition of STAT3 may also potentiate the effect of immune checkpoint inhibitors." (PMID 33786638, 2021). "Studies reported that AKT/STAT3 signaling pathway is involved with cancer metastasis 12-13." (PMID 33390776, 2021). "Therefore, involvement of STAT3 needs to be explored at the molecular level in the subjects suffering with both, cancer and diabetes." (PMID 34535145, 2021). "We also examined STAT3 expression in cancer tissues by qRT-PCR." (PMID 34321456, 2021). "The IL-6/JAK/STAT3 pathway has a key role in the growth and development of many human cancers." (PMID 33725976, 2021). "Phosphorylated STAT3 also promotes cancer stem cells (CSCs) self-renewal and differentiation." (PMID 33753770, 2021). "However, it is unlikely that they operate independently of the transcriptional activity of STAT3, which is extensively established to have a key role in generating an anti-inflammatory environment conducive for infection or cancer outgrowth." (PMID 34777338, 2021). "The canonical STAT3 pathway that functions transiently and is strictly regulated in normal cells, has been documented to be persistently activated in a variety of solid and hematological malignancies." (PMID 34440220, 2021). "In addition, FOXM1B/C have been demonstrated to promote cancer progression through the interaction with other proteins, such as β‐catenin, STAT3, SMAD3, HSP70, nucleophosmin (NPM), maternal embryonic leucine‐zipper kinase (MELK), and Pin1." (PMID 33314660, 2021). "Moreover, cyclization of the salicylanilide core scaffold of NSC765690 mediated its higher anti-cancer activities and had greater potential to interact with STAT3/CDK2/4/6 than did NSC765599 with an open-ring structure." (PMID 33477856, 2021). "Therefore, the IL-6/STAT3 pathway is a pharmacological target for treating human diseases, cancer included." (PMID 33806019, 2021). "The direct effect of STAT3 targeting depends on the genetic background of cancer cells." (PMID 34067832, 2021). "In a cancer environment, STAT3 can be a significant contributor to tumourigenic activity." (PMID 34829751, 2021). "As such, through its role in STAT3 phosphorylation, Hsp110 may regulate apoptosis and cancer development." (PMID 33525518, 2021).
cancer (continued). "Targeting STAT3 signaling by small molecules might be a potential strategy for the treatment of human cancer." (PMID 34257541, 2021). "Therefore, inhibiting STAT3-mediated MDR1 gene expression is a possible treatment option for drug-resistant cancers." (PMID 33946916, 2021). "We discovered that senescence-like CAF CM could reduce IR-induced apoptosis of cancer cells compared with the IR control group, and inhibition of STAT3 could reverse this phenomenon." (PMID 34877934, 2021). "The IL-6/JAK/STAT3 pathway is important to the growth and advancement of many human cancers." (PMID 34552929, 2021). "Hence, curcumin blocked STAT3-mediated signaling, which contributed to the suppression of the cancer stem cell phenotype in TNBC." (PMID 34298639, 2021). "In addition, inhibition of JAK2/STAT3 signaling by introducing AG490 attenuated the cancer-promoting activity of THAP9-AS1." (PMID 34691358, 2021). "Our study provides an alternative strategy for the therapy of cancers related to STAT3." (PMID 33531691, 2021). "Among chromone derivatives, 3-formylchromone (3FC) and its derivatives have been reported to induce cytotoxicity in various cancer models by targeting diverse cellular targets such as STAT3, thymidine phosphorylase, DNA topoisomerase IIα, and the reversing of multidrug resistance." (PMID 35053027, 2021). "Furthermore, IL-6 plays a crucial role in cancer progression by activating STAT3 and stimulating the proliferation and migration cancer cells." (PMID 33917793, 2021). "However, the study in somatic cancer cell lines indicated that GlcN elicits the anti-cancer effect via the downregulation of STAT3 and ERK1/2 pathways." (PMID 34901113, 2021). "STAT‐3 is another transcription factor that is critical for cancer progression and chemoresistance." (PMID 34766149, 2021). "However, since STAT3 also plays essential roles in both normal cells and cancer cells in various biological processes, targeting STAT3 is not clinically achievable." (PMID 33937225, 2021). "Since STAT3 was discovered in 1994, most studies have mainly focused on its potential in the survival, proliferation, angiogenesis, migration, invasion and immune suppression of cancer cells." (PMID 34076564, 2021). "Recently some compounds are targeting PD-L1 and/or STAT3 for cancer therapy." (PMID 34440920, 2021). "Besides, due to the notion that STAT1 and STAT3 play opposite role in cancer-relevant processes, we also evaluated the expression of STAT3 in our experimental models." (PMID 34642300, 2021). "Furthermore, we investigated the effect of V-ATPase inhibition with bafilomycin A on STAT3 overexpressed cancer cells." (PMID 34234852, 2021). "STAT3 and STAT5 are also commonly mutated a variety of cancers." (PMID 34867402, 2021). "However, further studies are required to decipher the exact mechanism of STAT3 suppression by PL and its analogs which pave the way in developing therapies against different cancers." (PMID 36046754, 2021). "Stat3 is reported to be activated in many cancers and to influence patient survival." (PMID 34766149, 2021). "The activation of STAT3 pathway and the high level of glycolysis could facilitate the progression of cancer cells." (PMID 34195079, 2021). "Nevertheless, our present findings suggest that direct inhibition of STAT3 activity with silibinin might represent a promising clinical strategy to circumvent NSCLC cancer cell-intrinsic nintedanib resistance." (PMID 34439322, 2021). "Their group further observed that exposure of macrophages to apoptotic MCF-7 cells increases the production of IL-6 and activation of STAT3, which may be responsible for increased cancer stem cell populations and metastasis." (PMID 34207035, 2021). "Targeting the STAT3 signalling could be a novel approach to prevent and/or treat cancers since p-STAT3 contributes to malignant transformation and progression." (PMID 34078370, 2021).
cancer (continued). "Furthermore, YHO-1701 downregulated p-STAT3 expression in all cancer cell lines, consistent with the previous observation that YHO-1701 also inactivated the STAT3 signaling pathway in SAS cells." (PMID 33758275, 2021). "To determine whether STAT3 activation in PTEN-deficient cancer cells can also limit the effects of PI3K/AKT/mTOR inhibitors, we knocked down STAT3 in the HGC-27, MDA-MB436, and 786-O cells, and treated the wild-type and knockdown cells with BEZ235." (PMID 33431808, 2021). "Further analyses of the functions of the CDCP1-Src-Met-STAT3 pathway in a wide range of cancer cells may reveal potentially new therapeutic targets for the treatment of some malignant cancers." (PMID 33574034, 2021). "The results suggested that EVs from cancer cells might induce M2 macrophages through the STAT3 pathway." (PMID 33509150, 2021). "Collectively, these results suggest that 5-epi-sinuleptolide could inhibit the activities of key regulators for cancer progression including JAK2/STAT3, AKT, and ERK1/2, and suppress the invasiveness of malignant pancreatic cells." (PMID 34834023, 2021). "STAT3 has been suggested as a promising drug target for several types of cancer." (PMID 33786638, 2021). "Therefore, we explored associations of CDK2/4/6/STAT3 expressions with infiltrating immune cells (CD4+ T cells, B cells, CD8+ T cells, neutrophils, dendritic cells, and macrophages) in multiple cancers." (PMID 33668805, 2021). "Besides, in different types of tumors, another transcriptional target of STAT3 has emerged for its importance in conferring radioresistance to the cancer cells: Forkhead box protein M1 (FOXM1)." (PMID 34141616, 2021). "The classical and alternative IL-6 signaling pathways activate JAKs with subsequent activation of the signal transducer and activator of transcription-3 (STAT3), a key transcription factor inducing numerous effector genes involved in cancer promotion and malignancy." (PMID 34445170, 2021). "Although the structure of STAT3 is known, the molecular details of changes in DNA-binding properties of mutated STAT3 and their relationship with human diseases including cancers is not clear." (PMID 33535185, 2021). "Dysregulated or constitutive activation of STAT3 may lead to adverse functional effects, such as impaired immunity and the development of inflammatory disease and cancers." (PMID 33382511, 2021). "Particularly, the activation of the IL-6/JAK/STAT3 core axis is observed in many types of cancer." (PMID 34440220, 2021). "Indeed, MDSCs secretes IL-6, which induces STAT3 phosphorylation, and activates Notch signaling, which enforces IL-6/STAT3 activation, thereby affecting cancer stemness." (PMID 35582386, 2021). "STAT3 has been shown to promote cancer proliferation, migration, invasion, and angiogenesis." (PMID 34638797, 2021). "Our recent studies have identified STAT3 and NF-κB RelA (also known as p65), 2 master inflammatory transcription factors that also function as proto-oncogenes in lung and many other cancers, as the intrinsic drivers of lung macrophage protumorigenic activities." (PMID 33539325, 2021). "STAT3 is reported to promote the mitochondrial respiration in cancer stem cells (CSC)." (PMID 34785656, 2021). "Moreover, EBV can initiate carcinogenesis by inducing chronic inflammation via NF-κB and signal transducer and activator of transcription 3 (STAT3) signalling to create a chronic inflammatory microenvironment that supports cancer development." (PMID 33918087, 2021). "IL-11 in turn activates GP130/STAT3 in cancer cells to initiate metastasis." (PMID 36046433, 2021). "With the same experimental design but in wild type mice, lycopene significantly exhibited anti-cancer property, mainly by inhibition of proinflammatory signaling as seen in significant reduction in phosphorylation of NF-κB p65, STAT3, IL-6 and suppressed inflammatory foci." (PMID 34202203, 2021).
cancer (continued). "In addition to its established role as a transcription factor in cancer, signal transducer and activator of transcription 3 (STAT3) regulate mitochondrion functions and gene expression through epigenetic regulation." (PMID 33523587, 2021). "It has been also observed that acetylation in K87 may favor the translocation in mitochondria of STAT3 in starved cancer cells after serum reintroduction or insulin stimulation." (PMID 34642818, 2021). "It is possible that other IL-6-like signals that activate the JAK2/STAT3 pathway are mediating some of the suppression in other cancer cells as treatment of cGAMP-unresponsive cancer cells with the JAK2/STAT3 inhibitor WP1066 upregulated type I IFN expression in the tested cancer cells." (PMID 33790360, 2021). "Hyperactivation of STAT3 plays an important role in numerous malignant tumors 19-20." (PMID 33767595, 2021). "Therefore, the termination of the deregulated STAT3 cascade is an attractive therapeutic approach to counterbalancing the oncogenic and prosurvival effects of STAT3 in human cancers." (PMID 35053027, 2021). "Owing to the oncogenic property of STAT3 it has a vital role in cancer." (PMID 34199460, 2021). "Furthermore, JAK2/STAT3 signaling pathway involved in regulating the proliferation and apoptosis in a variety of cancer cells." (PMID 33995073, 2021). "Therefore, our findings suggest that Anwulignan can inhibit NSCLC cancer growth by inhibiting the JAK1/STAT3 signalling pathway." (PMID 33523587, 2021). "In the present study, we observed that CKS1B could also positively regulate STAT3/PD‐L1 signaling in PTC cells, and the inhibition of CKS1B could suppress cancer development of PTC by regulating STAT3/PD‐L1 signaling." (PMID 32960462, 2021). "According to recent studies, JAK2/STAT3 signaling pathway played critical roles in metastasis and progression of cancers, which implied that JAK2 might be a crucial therapeutic target for treatment of cancer." (PMID 33917914, 2021). "Activation of the IL-6/STAT3 pathway can block antitumour immunity in cancers." (PMID 33855091, 2021). "Restoration of STING activity by for example blocking JAK2/STAT3 pathways may increase the efficacy of cancer immunotherapies in particular therapies using STING agonists." (PMID 33790360, 2021). "Thus, in addition to serving as a co-activator for TEAD proteins, YAP and TAZ are also co-activators for AP-1 proteins and STAT3, with both classes of target sites playing important roles in cancer." (PMID 34463254, 2021). "Moreover, silencing of PDS5B expression promotes cell proliferation via induction of IL-6 secretion and activation of STAT3, and promotion of cyclin D1 expression in human cancer." (PMID 34226509, 2021). "STAT3 is also a multifunctional transcriptional factor with an important implicative role in cancer progression and drug resistance and has been extensively explored in cancer therapy." (PMID 33668805, 2021). "The JAK/STAT3 signaling pathway plays a critical role in cancers." (PMID 34330232, 2021). "Additionally, cancer and stromal cells produce various inflammatory cytokines, such as IL-1, IL-6, and IL-8, which in turn activate STAT3/NF-κB pathways in both cancer and stromal cells." (PMID 35006395, 2021). "Recent advances in the oncogenic function of STAT3 indicate that STAT3 inhibitors may be a highly promising potential therapeutic cancer intervention." (PMID 34407787, 2021). "Consistent with this hypothesis, STAT3 knockdown significantly augmented the BEZ235-induced decrease in the viability of cancer cells." (PMID 33431808, 2021). "Interestingly, activation of STAT3 has emerged as a mechanism of resistance to multiple TKIs in various cancer models and inhibiting STAT3 increases treatment efficacy." (PMID 34885140, 2021). "Overexpression of GGH may be associated with dysregulation of multiple cancer-related gene pathways, including those involved in cell cycle regulation, cell motility, MAPK, STAT3, and KRAS signaling, and immune responses." (PMID 35082830, 2021).
cancer (continued). "STAT3 activity is known to regulate sensitivity to TRAIL-induced apoptosis in cancer cells." (PMID 34543231, 2021). "Moreover, Stattic is a multi-kinase inhibitor targeting STAT3 in the preclinical phase that shows the potential to reduce cancer cell survival, proliferation, and invasiveness." (PMID 34639131, 2021). "Inhibition of STAT3 pathway activation can induce apoptosis in cancer cells." (PMID 33380422, 2021). "In the cancer-bone microenvironment, STAT3 signaling is essential for cell migration and viability." (PMID 34638338, 2021). "Interestingly, the expression levels of four genes (PDGFB, CCND2, CTF1, IL7R) identified in the current study were strongly associated with STAT3 activation, clinical outcome of LUAD patients and drugs sensitivity across cancer cell lines in GDSC." (PMID 34301211, 2021). "Of the seven members of the signal transducer and activator of transcription family proteins (STAT 1, 2, 3, 4, 5a, 5b, and 6), STAT3 is known as both a transcription factor and an oncogene, and is considered to be one of the most important regulators for cancer progression." (PMID 33753770, 2021). "Therefore, despite strong experimental indications, the role of IL-6-mediated induction of STAT3 activity remains to be proven in cancer cachexia patients." (PMID 33419963, 2021). "Interestingly, a previous study showed that when JAK2/STAT3 signaling pathway is activated, cancer cells tend to escape the immune surveillance and metastasize to distant organs through blood circulation, resulting in the formation of metastatic lesions." (PMID 34895038, 2021). "The JAK/STAT3 signaling pathway plays crucial roles in various types of cancer." (PMID 34722553, 2021). "Therefore, it is likely that STAT3 inhibition by YHO-1701 has pleiotropic effects in cancer therapy; tackling this subject is one of our future research directions." (PMID 33758275, 2021). "Furthermore, the c-Myc cofactor PIM1 was identified as an IL-6/STAT3 downstream mediator of the acquisition of EMT and CSC-associated features in cancer cells, suggesting a role for c-Myc on IL-6/OSM-promoted EMP." (PMID 34361105, 2021). "Therefore, activated STAT3 can promote the invasion and metastasis of cancer cells by mediating the EMT process." (PMID 33462379, 2021). "Importantly, blocking STAT3 signaling in cancer cells inhibited the expression of two members of the V-ATPase family - ATP6V1B2 and ATP6V0D1." (PMID 34234852, 2021). "Immunohistochemistry and immunofluorescence analyses indicated that activation of the STAT3 and NF-κB pathways in MDSCs may be a potential mechanism for cancer progression." (PMID 33854974, 2021). "The IL-6/JAK2/STAT3 pathway plays a crucial role in the growth and development of many cancers." (PMID 34277446, 2021). "Additionally, STAT3 and CDK6 have been associated with cancer-associated fibroblast and immune cell infiltration and are considered biomarkers of poor prognosis in multiple cancers." (PMID 34572040, 2021). "Generally, CKS1B/STAT3 axis accounts for cancer development." (PMID 32960462, 2021). "It is noteworthy, that some of the transcription factors which have been previously linked to EZH2 activation, albeit in other cancer entities, underlie transcriptional control by NFATc1 (MYC, STAT3) or represent well-characterized NFATc1 partner proteins (STAT3, ELK1)." (PMID 34943970, 2021). "All these recent discoveries point to new directions for targeting STAT3 in cancer treatment." (PMID 33259114, 2021). "Moreover, piperine affects diverse signaling pathways associated with cancer cell growth and survival, including mitogen-activated protein kinase (MAPK), PI3K/Akt, and STAT3 pathways." (PMID 33921897, 2021). "STAT3 is being investigated as potential target for cancer treatment." (PMID 33380422, 2021). "Moreover, some years ago, it has been proposed that STAT3 can also be involved in the resistance of cancer cells to IR." (PMID 34141616, 2021).